ANGPTL4 (angiopoietin like 4)
Diseases named in the same sentence as ANGPTL4 in open-access papers (continued):
Sharing a sentence is not in itself a finding about the gene and the disease.
musculoskeletal disease (2 papers, 2017 to 2024). "Moreover, ANGPTL4 is linked to musculoskeletal diseases, including OA, and influences processes such as bone resorption, cartilage degradation, angiogenesis, and vascular permeability." (PMID 39176085, 2024). "This will highlight ANGPTL4 as a regulator of multiple disease processes, which could represent a novel therapeutic target in osteolytic musculoskeletal disease." (PMID 28458654, 2017).
colorectal (1 paper, 2025). "Collectively, these findings provide strong and consistent support for a potential role of ANGPTL4 in colorectal tumorigenesis." (PMID 40511612, 2025).
hematological cancers (1 paper, 2025). "These drugs are mainly used in hematological malignancies and could further implicate ANGPTL4’s involvement in hematological cancers." (PMID 40233044, 2025).
ANGPTL4 also shares sentences with these, for which no sentence is quoted: peritonitis (4 papers); acute myocardial infarction (3); colorectal tumor (3); focal segmental glomerulosclerosis (3); IgA nephropathy (3); adenocarcinoma (2); ankylosing spondylitis (2); cerebral malaria (2); chronic obstructive pulmonary disease (2); gastric tumor (2); idiopathic pulmonary fibrosis (2); meningitis (2); nonalcoholic fatty liver disease (2); obstructive sleep apnea (2); oral squamous cell carcinoma (2); osteoporosis (2); ovarian clear cell cancer (2); tuberculous spondylitis (2); acne (1); acute coronary syndrome (1); adrenocortical carcinoma (1); age-related macular degeneration (1); amyloidosis (1); Anorexia (1); anorexia nervosa (1); aristolochic acid nephropathy (1); basal cell carcinoma (1); bladder tumours (1); bone metastasis (1); brain tumor (1).
A further 67 diseases each share a sentence with ANGPTL4 in 1 paper.